ENSG00000264058 (novel transcript)
Gene: Protein-coding gene on chromosome 17 (40,627,356 to 40,665,141, reverse strand). Ensembl gene ENSG00000264058.
Genetic constraint (gnomAD): Missense variants: 307 observed, 323.74 expected, observed/expected ratio (o/e) 0.95, 90% interval 0.86 to 1.04. Synonymous variants: 99 observed, 113.46 expected, observed/expected ratio (o/e) 0.87, 90% interval 0.74 to 1.03.